EGF (epidermal growth factor)
Diseases named in the same sentence as EGF in open-access papers (continued):
Sharing a sentence is not in itself a finding about the gene and the disease.
medulloblastoma (9 papers, 2010 to 2022). A malignant, invasive embryonal neoplasm arising from the cerebellum. "While it remains to be determined, it is possible that in medulloblastoma cells as well, loss of Na,K-ATPase function could modulate RhoA or Rac1 activity to inhibit EGF-induced motility and stress fiber formation." (PMID 25052069, 2014). "Na,K-ATPase has been proposed to act as a signaling scaffold and our studies suggest that in medulloblastoma cells Na,K-ATPase might act as a check point to integrate EGF-associated signaling pathways." (PMID 25052069, 2014). "Medulloblastoma-associated CSCs selected by serum-free medium with bFGF and EGF can form 3 D spheroids and display enhanced self-renewal and highly co-expressed stem cell genes (Oct4, Nanog, Nestin, and Musashi-1) as well as anti-apoptotic genes (Bcl-2 and Bcl-XL)." (PMID 20718984, 2010). "Then, human medulloblastoma Daoy cells were treated with 4 different conditions: Control, EGF (5 ng/ml), Shh-N conditioned media, and EGF plus Shh-N conditioned media." (PMID 32341755, 2020). "Results showed that medulloblastoma cells gain motility at initially elevated concentrations of EGF (mimicking the paracrine situation) and become less motile with decreasing concentration gradient fields." (PMID 29882823, 2018). "We recently showed that ouabain inhibits EGF-induced actin stress fiber formation and cell motility in medulloblastoma cells." (PMID 26382850, 2015). "We recently showed that ouabain inhibits EGF-induced Erk1/2 and Akt activation and prevents EGF-induced formation of actin stress fibers and cell motility in medulloblastoma cells." (PMID 26382850, 2015). "In the present study, we examined the effects of the cardiac glycoside ouabain on EGF-induced signaling in medulloblastoma cells." (PMID 25052069, 2014). "Here, we show that in medulloblastoma cells, both EGF and ouabain activate Erk1/2 and PI3K/Akt signaling." (PMID 25052069, 2014). "EGF is known to regulate cell migration in a variety of cell types, including cerebellar granule neurons 31 from which medulloblastoma is thought to derive." (PMID 25052069, 2014). "In 2015, a group used the microfluidic device μLane to image the real-time migratory responses of individual medulloblastoma cells within microenvironments of defined epidermal growth factor (EGF) and stromal cell-derived factor 1-alpha (SDF-1) gradient profiles." (PMID 29882823, 2018). "The group explained that their system induces medulloblastoma cells into becoming motile at high EGF concentrations, but that this motility is slowed down as migrating cells approach fields with lower gradients (despite possible greater chemoattractant concentrations)." (PMID 29882823, 2018). "In addition, we provide evidence that ouabain attenuated the formation of EGF-induced stress fibers and inhibited motility in medulloblastoma cells." (PMID 25052069, 2014). "Nevertheless, in the presence of ouabain, EGF did not induce the characteristic phospho-FAK staining observed in DAOY cells treated with EGF alone, suggesting that ouabain might prevent EGF-induced cell migration in medulloblastoma cells." (PMID 25052069, 2014). "Here, we show that consistent with previous studies, treatment of DAOY medulloblastoma cells with EGF activated the EGFR signaling cascade and resulted in increased phosphorylation of both the EGFR and the HER2/ErbB2 receptors as well as the downstream targets Erk1/2 and Akt." (PMID 25052069, 2014). "CSCs in FSmoM2;hGFAP-cre medulloblastomas depend on bFGF/EGF and not SHH, similar to their cell of origin (NSCs), and they are insensitive to SHH inhibition, even though the SHH pathway is highly activated in bulk tumor cells in this model." (PMID 36688010, 2022).
medulloblastoma (continued). "Ouabain, an Na,K-ATPase inhibitor, inhibited EGF induced medulloblastoma cell motility in a wound healing assay, prevented formation of EGF-induced actin stress fibers, and inhibited EGF-induced phospho-focal adhesion kinase (FAK) localization to the lamellipodia of medulloblastoma cells." (PMID 25852478, 2015). "The present study investigated the role of micro-environmental growth factors expressed in the brain, such as HGF and EGF, in relation to the effects of hepatocyte growth factor receptor (MET) and epidermal growth factor receptor family (ErbB1-4) inhibition in medulloblastoma cell lines." (PMID 26496080, 2015). "Taken together, these data show that EGFR/HER2 signaling can be activated by EGF in DAOY cells and thus, DAOY cells may serve as a suitable model to test the effect of cardiac glycosides on EGFR signaling in medulloblastoma." (PMID 25052069, 2014). "Whereas VEGF-A, PDGF-AB, FGF-2 and EGF show weak bypassing potential in addition to either crizotinib or canertinib, addition of HGF shows strong bypassing potential by significantly bypassing the growth-inhibitory effects of canertinib in medulloblastoma cells." (PMID 26496080, 2015). "ErbB2 has been suggested to be involved in the migration of medulloblastoma cells 2,9,10, and in our studies DAOY cells treated with EGF were highly motile, suggesting that activation of the EGFR signaling cascade may play a role in medulloblastoma cell migration." (PMID 25052069, 2014). "In addition, in D283 cells, a cell line derived from medulloblastoma metastasis in the peritoneum, ouabain did not inhibit EGF-induced activation of Erk1/2 but reduced EGF-induced Akt activation and almost completely abolished EGF-induced EGFR phosphorylation." (PMID 25052069, 2014). "With its role in cell migration, relocation of FAK to stress fiber endpoints in EGF-treated cells supports the hypothesis that the EGFR signaling cascade might be involved in switching from random to directional movement, thus promoting tumor cell invasion in medulloblastoma cells." (PMID 25052069, 2014). "However, in medulloblastoma cells, ouabain did not transactivate EGFR as has been reported in other cell lines, and ouabain inhibited EGF-induced Erk1/2 and Akt activation." (PMID 25852478, 2015).
mesothelioma (9 papers, 2009 to 2024). A usually malignant and aggressive neoplasm of the mesothelium which is often associated with exposure to asbestos. "We then expanded the gene panel to include ITGA6, PD-L1, and MMP1, which were previously shown to be upregulated by EGF in EMT models of mesothelioma." (PMID 33777943, 2021). "The aim of this research was to implement a procedure for nimotuzumab radiolabeling to evaluate its biodistribution and affinity for EGF (epidermal growth factor) receptors present in a mesothelioma xenograft." (PMID 30501113, 2018). "This is particularly interesting in the light of our previous report where exposure of mesothelioma cells to EGF and IGF-1 inhibited expression of syndecan-1 and -2." (PMID 23144729, 2012). "Mesothelioma often up-regulated expression of vascular endothelial growth factor (VEGF), epidermal growth factor (EGF) and the corresponding receptors (VEGFR, EGFR)." (PMID 26191485, 2015). "We have derived and characterized four human mesothelioma cell cultures that retain tumor initiating cell properties, using the chemically defined medium MCDB201 supplemented with 2% FCS, EGF and FGF." (PMID 20175889, 2010). "Similar to the results presented here, dependency of EGF-stimulated migration on the MAPK pathway was previously reported in mesothelioma cell lines, albeit in the absence of oncogenic Ras." (PMID 33777943, 2021). "Molecular targeting agents that inhibit EGF/EGFR or VEGF/VEGFR pathway such as erlotinib, gefinitib and bevacizumab however failed to produce clinical benefits, but an inhibitor to block the HGF/c-Met pathway has not yet been examined for the efficacy to mesothelioma." (PMID 26191485, 2015).
mucositis (9 papers, 2009 to 2025). Mucositis is inflammation and damage of the mucous membranes lining the mouth and other parts of the gastrointestinal (GI) tract. "This study is the first to describe differences in EGF expression before and after mucosal seal formation and its association with the presence of peri-implant mucositis." (PMID 34682957, 2021). "Is there an association between EGF levels, loss of mucosal sealing, and development of peri-implant mucositis?" (PMID 34682957, 2021). "Low EGF levels in the peri-implant mucosa have been associated with the presence of marked mucosal inflammation, peri-implant mucositis, and loss of peri-implant mucosal sealing." (PMID 34682957, 2021). "According to clinical results and EGF expression, it can be observed that the increase in EGF is compatible with the presence of mucosal sealing, and its decrease in implant function is associated with the presence of mucositis." (PMID 34682957, 2021). "We hypothesized a correlation between high EGF levels and the presence of peri-implant mucosal integrity and, in contrast, low EGF levels are associated with peri-implant mucositis." (PMID 34682957, 2021). "The reduction of EGF was directly associated with increased frequency and severity of mucositis." (PMID 30322002, 2018). "Several biomarkers, including epidermal growth factor (EGF), C-reactive protein, TNF-alpha, and cytokines, have been linked to an increased incidence and severity of mucositis." (PMID 41333216, 2025). "Salivary EGF was decreased, and more severe mucositis was present, with statistically significant correlation." (PMID 41220465, 2025). "Salivary EGF was decreased, and more severe mucositis was present, with a statistically significant correlation." (PMID 41220465, 2025). "Increased EGF expression was reported post treatment and correlated with reduced oral mucositis occurrence." (PMID 41220465, 2025). "Salivary EGF was decreased post radiotherapy in most cases, and was correlated with worse oral mucositis." (PMID 41220465, 2025). "Futures therapies based on EGF clinical application in mucositis treatment should be investigated in futures researches." (PMID 34682957, 2021). "In the present study, we show that topical treatment of the oral mucosa with EGF is effective in patients with radiation-induced mucositis." (PMID 19456848, 2009). "Based on these biological properties, we tested the topical application of EGF for mucositis induced by anticancer therapy." (PMID 19456848, 2009). "Therefore, based on the biological function of EGF and the increased incidence of peri-implant mucositis, this study aimed to evaluate the correlation between the levels of epidermal growth factor (EGF) and its receptor (EGFR) at different stages." (PMID 34682957, 2021). "Additionally, treatment with EGF before and after irradiation has been proven to limit the manifestations of mucositis." (PMID 23379680, 2013). "Thus, the elevation of EGF levels after mucositis treatment may return to clinical signs compatible with health." (PMID 34682957, 2021). "This study aimed to evaluate the correlation between epidermal growth factor (EGF) and receptor (EGFR) levels in different clinical stages of dental implant rehabilitation and trace mucositis development’s biological profile." (PMID 34682957, 2021). "Based on our results, the low levels of EGF gene expression in the peri-implant crevicular fluid are related to the development of peri-implant mucositis and the absence of mucosae sealing." (PMID 34682957, 2021). "It was concluded that low levels of EGF gene expression in the peri-implant crevicular fluid are related to the development of peri-implant mucositis and the absence of mucosae sealing." (PMID 34682957, 2021).
mucositis (continued). "Some limitations found were the impossibility of characterizing peri-implant mucosal sealing, considering that the work was performed in humans, the lack of information on EGF levels after treatment of peri-implant mucositis, and the number of participants in the research." (PMID 34682957, 2021). "Thus, this cross-sectional study aimed to evaluate the correlation between the levels of epidermal growth factor (EGF) and its receptor (EGFR) in the different clinical phases that represent an evolution from the formation of mucosal sealing to the development of peri-implant mucositis." (PMID 34682957, 2021).
pancreatic ductal adenocarcinoma (9 papers, 2015 to 2025). An infiltrating adenocarcinoma that arises from the epithelial cells of the pancreas. "They expressed several tetraspanins, which are involved in the regulation of stemness in other cell types, including Tspan8 that is upregulated by SOX9 in pancreatic ductal adenocarcinoma in response to EGF stimulation." (PMID 37408269, 2023).
Anxiety (8 papers, 2009 to 2025). Intense feelings of nervousness, tension, or panic often arise in response to interpersonal stresses. "A potential confounding factor for the beneficial effects of EGF on cognition is whether EGF modulates anxiety-like behavior." (PMID 27788676, 2016). "The improved cognition with EGF compared to the VC was not related to general locomotion or anxiety like effects." (PMID 27788676, 2016).
atopic dermatitis (8 papers, 2018 to 2025). "Increased levels of TARC (Thymus and Activation-Regulated Chemokine) and EGF (Epidermal Growth Factor) have been linked to the pathogenesis of atopic dermatitis, a condition mediated by preferential Th2 recruitment." (PMID 41200192, 2025). "Epidermal Growth Factor is important for skin development and homeostasis, and EGF administration has been shown to suppress inflammation in mouse models of atopic dermatitis." (PMID 35878346, 2022). "Administration of EGF resulted in improved Th1/Th2 balance and inhibited mast cell hyperplasia, a major process in the induction of atopic dermatitis." (PMID 30093649, 2018). "Considering that AD is characterized by decreased AMPs with defective innate immune function, EGF is expected to be effective in restoring damaged immune barriers by improving defenses such as those provided by AMPs in patients with atopic dermatitis who are vulnerable to S. aureus." (PMID 29862299, 2018). "Our analysis found higher baseline levels of TARC and EGF in the SU2043 group, which also had a higher prevalence of atopic dermatitis (80%) compared to the SU4043 group (42.1%)." (PMID 41200192, 2025). "The epidermal growth factor (EGFR) on keratinocytes protects this barrier, and its dysfunction leads to atopic dermatitis-like skin disease." (PMID 34833113, 2021).
chronic atrophic gastritis (8 papers, 2012 to 2025). Atrophic gastritis that is persistent and long-standing. "The mechanism of NSAID-induced gastritis is impaired mucosal defense by decreased prostaglandin and inhibition of epithelial cell proliferation by suppressing epidermal growth factor, which eventually causes ulceration and bleeding in the stomach." (PMID 35454114, 2022). "Furthermore, this analysis demonstrated that an elevated level of EGF is detrimental for chief and parietal cells and is probably underlying the histologic condition of atrophic gastritis." (PMID 35408991, 2022). "This study showed that H. pylori infection induced gastritis by increasing gastric inflammation, IL-17, IL-33, and EGF production and decreasing PGE2 levels." (PMID 39857676, 2025). "We have found that biopsies of atrophic gastritis show elevated levels of EGF that correlate inversely with the detection of chief and parietal cell markers (PGC and ATP4B)." (PMID 35408991, 2022). "The expression levels of EGF in serum and urine from chronic atrophic gastritis patients were much higher than those in the control group." (PMID 35754680, 2022). "The reduction in gland size observed in atrophic gastritis might be due to the lack of chief and parietal cells that cannot differentiate due to the elevated level of EGF." (PMID 35408991, 2022).
chronic obstructive pulmonary disease (8 papers, 2018 to 2025). A chronic and progressive lung disorder characterized by the loss of elasticity of the bronchial tree and the air sacs, destruction of the air sacs wall, thickening of the bronchial wall, and mucous accumulation in the bronchial tree. "In a cohort of both healthy controls and chronic obstructive pulmonary disease patients, greater muscle EGF messenger ribonucleic acid (mRNA) expression was associated with fewer slow-twitch muscle fibres and lower VO2peak." (PMID 33723630, 2021). "Once released, active KLK1 may stimulate EGF signaling and increase oxidative stress susceptibility, processes implicated in chronic obstructive pulmonary disease (COPD) progression." (PMID 41516101, 2025). "We hope that these findings will open a new window in the treatment of EGF-related diseases such as acne, aging ulcers, glomerular kidney or chronic obstructive pulmonary diseases." (PMID 38094045, 2023). "The expression of EGF and its receptor is elevated in the bronchial epithelium of patients with chronic obstructive pulmonary disease (COPD)." (PMID 38397773, 2024).
dementia (8 papers, 2013 to 2026). Loss of intellectual abilities interfering with an individual's social and occupational functions. "IL-18 and epidermal growth factor levels were higher in Black individuals with a parental history of dementia compared to Hispanic individuals with the same history." (PMID 41968642, 2026). "The plasma content of EGF is significantly decreased in dementia patients, whereas supplementation with EGF strongly ameliorates cognitive defects in Aβ injured rats and senile rats." (PMID 23437202, 2013). "Furthermore, research focused on blood protein signatures recently revealed that epidermal growth factor (EGF), platelet-derived growth factor (PDG-BB) and macrophage inflammatory protein 1δ (MIP-1δ) differentiated AD from control subjects, but not from patients with other types of dementia." (PMID 23874844, 2013).
dermatitis (8 papers, 2016 to 2025). An inflammatory process affecting the skin. "According to a previous report in mice, this haemolysin affected the epidermal growth factor, which in turn caused skin inflammation." (PMID 40723946, 2025). "Abnormalities of the EGF–EGFR–ERK signaling pathway in keratinocytes cause skin disorders." (PMID 33096942, 2020). "Topical EGF improved inflammatory acne in a randomized clinical trial and enhanced barrier function to improve dermatitis phenotypes in mice." (PMID 39924511, 2025). "This is particularly relevant since there is growing interest in topical EGF as a potential treatment for EGFRI-induced skin inflammation and other inflammatory skin diseases like acne vulgaris." (PMID 39924511, 2025). "According to some studies, epidermal growth factor has demonstrated good effect and high safety in the treatment of dermatitis, wound healing, oropharyngeal and upper esophageal mucosal diseases, and some corneal or conjunctival mucosal lesions." (PMID 35130850, 2022). "Based on its potential roles, clinical trials to assess the therapeutic efficacy of EGF against diverse inflammatory diseases, including dermatitis, have been conducted." (PMID 32707897, 2020). "EGF treatment improved skin lesion severity, hyperkeratosis, ear and epidermal thickness, dermatitis score, and scratching behaviors of DNCB-treated NC/Nga mice." (PMID 30093649, 2018). "EGF treatment improved dermatitis score, ear thickness, epidermal hyperplasia, serum total immunoglobulin E level, and transepidermal water loss in NC/Nga mice with DNCB-induced AD." (PMID 30093649, 2018). "Treatment with EGF suppressed DNCB-induced AD-like skin inflammation." (PMID 30093649, 2018). "In addition, EGF decreased dermatitis score of DNCB-induced skin lesions on days 14 and 21 in a dose-dependent manner." (PMID 30093649, 2018). "Consequently, EGF treatment, and thus EGFR-signaling stimulation, might be protective in AD as it reduced skin inflammation of AD-like lesions in mice, enhanced skin barrier function, and improved Th1, Th2, and Th17 immune responses." (PMID 38675137, 2024).